EPHA2 (EPH receptor A2)
Diseases named in the same sentence as EPHA2 in open-access papers (continued):
Sharing a sentence is not in itself a finding about the gene and the disease.
cancer (continued). "Recent reports suggest that EphA2 is frequently overexpressed and often functionally dysregulated in advanced cancers, where it contributes to multiple aspects of malignant character." (PMID 15563374, 2004). "EphA2, a receptor tyrosine kinase, is overexpressed in various cancers." (PMID 41655696, 2026). "Flow cytometry analysis showed that ATG9A KO did not alter the expression of key phagocytosis checkpoints (MHC-I, PD-L1, CD24, CD47) or the CAR target EphA2, suggesting ATG9A regulates cancer cell susceptibility to macrophage killing through a specific and independent mechanism." (PMID 40595560, 2025). "Additionally, further exploration of CAR-T/NK cells in a broader range of EphA2-positive cancer models is warranted to validate their clinical applicability." (PMID 40181964, 2025). "To determine whether ATG9A KO-induced sensitization depends on direct cancer-macrophage contact, we conducted co-culture experiments with a 0.4 μM pore insert segregating α-EphA2-CAR-Ms on top." (PMID 40595560, 2025). "The class-switched and defucosylated type Ea2Mab-7 could contribute to treating EphA2-positive cancers in preclinical studies." (PMID 40236294, 2025). "It would be interesting to investigate whether the cytoplasmic localization of EphA2 is involved in the malignant properties of cancer cells." (PMID 40236294, 2025). "Other studies suggest that using bispecific antibodies in combination with other cancer therapies can be more effective in treating cancer and reduce the risk of resistance as it is designed to detect EGFR and EPHA2 proteins, which are located on the cancer cells’ surface." (PMID 40650799, 2025). "As a tumor-associated antigen, EphA2 has been extensively studied over the past 25 years, establishing its status as a promising molecular target for therapeutic development and clinical translation in NSCLC and other cancers." (PMID 40181964, 2025). "Currently, the functional meaning of the SASH1-Sam1/EphA2-Sam complex is unknown, but EphA2 is a well-established and crucial player in cancer onset and progression." (PMID 39942820, 2025). "EphA2 is a promising theranostics target for potential application in various types of cancer." (PMID 39934299, 2025). "Therefore, EphA2 is a promising target in cancer therapy because of its relatively low levels in most normal adult tissues." (PMID 40236294, 2025). "EphA2 has been shown to regulate VE-cadherin-mediated signalling and matrix degradation, while CD34 expression has been linked to endothelial-like phenotypes in aggressive cancers." (PMID 41228228, 2025). "Conversely, in cancer cells, ephrin A1 is often underexpressed while EphA2 becomes overexpressed." (PMID 41440001, 2025). "Thus, the synthetic Abs generated here will allow further exploration of the therapeutic potential of inhibitors targeting EphA2 in cancer and infectious disease." (PMID 40411427, 2025). "Interestingly, EPHA2 expression is upregulated during AMP-activated protein kinase (AMPK)-dependent metabolic cancer cell reprogramming and co-expression of AMPK and EPHA2 in CRC tumors is correlated with higher CD3+ T cell infiltration." (PMID 40148988, 2025). "The dysregulation of the EphA2-ephrins axis contributes to various diseases, including cancers." (PMID 40236294, 2025). "The roles of EPHA2 in cancer cell proliferation, migration and stemness have been well studied." (PMID 40919148, 2025). "Our analyses indicate that higher EphA2 expression are associated with significantly worse 5‐year survival rates in OS and RMS patients as compared to patients with lower EphA2 expression, suggesting that this receptor is a promising target for therapeutic intervention in these cancers." (PMID 39763064, 2025). "Although the specific signaling mechanism of how EphA2 regulates responses in OS cells is unknown, previous reports in other cancer types highlight a ligand-independent pro-oncogenic mode of action of the EphA2 receptor." (PMID 39056783, 2024).
cancer (continued). "EphA2 was found to be enriched in a specific subpopulation of EVs from various cancer cells." (PMID 38534339, 2024). "Furthermore, not only are EVs released by drug-resistant cancer cells enriched with EphA2, but they also transmit the invasive and metastatic phenotype from drug-resistant to sensitive cancer cells." (PMID 38534339, 2024). "Conversely, OS positively correlated with EphA2 expression in six cancers." (PMID 39596256, 2024). "Knockdown of EPHA2 inhibited the migration and invasion of cancer cells." (PMID 39567474, 2024). "Since activated ERK and RSK proteins can enhance the phosphorylation of EphA2 at S897, this could provide further support to cancer cell survival when EphA2 is present." (PMID 39056783, 2024). "Additionally, clinical samples from patients with basal-like BCA exhibiting phosphorylated EphA2 (pS897) were found to have the lowest response rates to neoadjuvant treatments and exhibited increased cancer stemness." (PMID 38612592, 2024). "EphA2 is considered an important molecular target for clinical translation in cancer treatment." (PMID 38279277, 2024). "When these CAR-T cells were coupled with another group of CAR-T cells that targeted the EphA2 antigen on the A549 cancer cells, significantly improved antitumor activity and survival rates in the mice were observed compared to the treatment with EphA2-specific CAR-T cells alone." (PMID 37877819, 2024). "The receptor tyrosine kinase EphA2 drives cancer malignancy by facilitating metastasis." (PMID 38915729, 2024). "A comparison of the EphA2 levels between the healthy group and each stage (I–IV) of cancer patients revealed that the EphA2 levels were significantly higher in cancer patients (healthy individuals vs. Stages I, II, III, IV; p = 0.00298, p = 0.00000734, p = 0.000254, p = 0.000542, respectively)." (PMID 39766211, 2024). "However, targeting EphA2 in cancer requires a deep understanding of its dual function and the intrinsic complexities of EphA2 signaling pathways." (PMID 39596256, 2024). "In cancer cells, EphA2 overexpression is often coupled with low ephrinA1 expression." (PMID 39596256, 2024). "This undesirable result may be because EphA2 promotes cancer development and progression in multiple ways, such as by promoting cancer cell proliferation, angiogenesis, and metastasis and facilitating the survival of CSCs." (PMID 38916835, 2024). "Expanding research on the measurement of serum EphA2 and its significance could pave the way for the real-time monitoring of cancer progression and further utilization as a therapeutic target in the future." (PMID 39766211, 2024). "The receptor tyrosine kinase ephrin type-A receptor 2 (EphA2) is overexpressed in malignant tumors." (PMID 37059179, 2023). "There are two deployable mechanisms by which EphA2 system could be used for targeted cancer treatment: by decreasing EphA2 expression or promoting EphA2 degradation, and blocking endogenous EphA2 activation." (PMID 37530973, 2023). "Inhibition of EphA2 by different genetic or pharmacological approaches has been shown to suppress tumorigenesis, suggesting that EphA2 is a promising therapeutic target to treat diverse malignant cancers." (PMID 37816703, 2023). "EphA2 is a member of the Eph family of RTKs and its role in cancer is controversial." (PMID 36980592, 2023). "Combining schisandrin C to recover the phosphorylation of EphA2 Ser897 may be a safe and effective strategy for cancer treatment." (PMID 37179400, 2023). "Therefore, EphA2 binders can inhibit cancer cells’ growth blocking EphA2 activity both by the means of its degradation (agonist binders) and by the means of the inhibition of Eph–ephrin interactions (antagonist binders)." (PMID 37895923, 2023).
cancer (continued). "For this reason, it is not surprising that newly synthesized molecules, endowed with agonist or antagonist properties, were pharmacologically characterized in prostate cell lines and, in particular, in PC3 cells, naturally overexpressing EphA2, the most studied Eph receptor in cancer." (PMID 37895923, 2023). "Alternatively, the differential phosphorylation of EphA2 determines the effect on tumorigenesis; EphA2-S897 phosphorylation promotes tumorigenesis, while EphA2-Y772 phosphorylation decreases transendothelial cell migration of cancer cells." (PMID 37816703, 2023). "EFNA1 belongs to the subfamily of ephrins acting as the ligands for Eph receptors, and the interaction of EFNA1 with its most common receptor EphA2 is deemed crucial to the onset of malignant tumors, possibly via regulation of cell cytoskeleton and cell adhesion." (PMID 37449541, 2023). "EphA2 is found at relatively lower levels in normal adult tissue, and this may indicate that it has potential for application in the treatment of cancer." (PMID 37612696, 2023). "Thus, the close correlation of EphA2 expression and function with malignancy makes this protein an important target for cancer therapy." (PMID 37063424, 2023). "Several studies suggest that EPHA2 has the potential to be an attractive target for cancer therapy." (PMID 35673569, 2022). "In many cases, ligand-induced EphA2 signaling has been recognized as antioncogenic, and thus agents that activate EphA2 could be useful as cancer therapeutics." (PMID 35970390, 2022). "EphA2 is a receptor that is overexpressed in various cancer cells." (PMID 35890274, 2022). "An analysis of differentially expressed genes revealed that EphA2 may exert its cancer-promoting effect through C-X-C motif chemokine ligand 11 (CXCL11)." (PMID 36478746, 2022). "Consequently, in addition to its functional relevance in malignancies, EPHA2 is considered as a liaison to deliver therapeutics to cancer cells." (PMID 35055192, 2022). "Considering that inhibition of heterotypic Sam-Sam interactions involving EphA2 could be a promising route in cancer therapy, during the last few years, we centered our research activities on the design of peptides able to hamper these interactions." (PMID 36142306, 2022). "Because suchagents would also cause receptor internalization, these could be additionallydeployed as carrying molecules for selective targeted delivery ofchemotherapy to EphA2-expressing cancers." (PMID 36331527, 2022). "For vinorelbine, EPHA2 codes for EPH receptor A2, a tyrosine kinase involved in cancer-related signaling, while NGEF codes for a guanine nucleotide exchange factor associated with signaling from EPH receptor A2, RhoA, Rac1 and CDC42 as well as cellular transformation and tumorigenesis." (PMID 36139690, 2022). "Some studies have reported the carcinogenic mechanism of EphA2 in some malignant tumors." (PMID 36478746, 2022). "It has been reported that EphA2 binds to EGFR in human cancer cell lines." (PMID 35668076, 2022). "Meanwhile, some key VM-related molecules have been investigated in various aggressive malignant tumors, including hypoxia-inducible factors, Ephrin type-A receptor 2 (EphA2) vascular endothelial growth factor (VEGF, also called VEGFA), and matrix metalloproteinases." (PMID 35595748, 2022). "Our results suggest that when resistance to cancer treatments targeting Ras signaling arises, the observed re-activation of Ras may have been due to an increase in the levels of the EphA2 / EGFR / Ephexin1 complex." (PMID 35668076, 2022). "It turns out that the shedding of EphA2 by MT1-MMP was one of the mechanisms promoting cancer." (PMID 36132127, 2022). "Numerous studies proposed the crosstalk between EPHA2-EGFR-PI3K signaling in cancer." (PMID 36297233, 2022). "Therefore, a combination treatment that includes an Ephexin1-specific inhibitor and targeted inhibitors of EGFR, EphA2, or K-Ras is predicted to improve the effectiveness of cancer treatment." (PMID 35668076, 2022).
cancer (continued). "The prominent role of EPHA2 in cancer attracted our attention." (PMID 35410462, 2022). "Existing studies have reported a variety of cancer-promoting mechanisms related to EphA2." (PMID 36478746, 2022). "Concerning the regulatory role of EphA2 in cancer radioresistance, it has been described that blocking EphA2 could suppress the radioresistance of NSCLC cells, as well as the migration, proliferation, and invasion of malignant cells." (PMID 36090890, 2022). "Therefore, we should pay attention to the interpretation of results for measurement of EphA2 in patients with comorbid cancer." (PMID 36553030, 2022). "EphA2 interacts in cis with different molecules, from growth factors to adhesion molecules to regulate cell adhesion and migration, especially in the context of cancer development and progression." (PMID 35096972, 2021). "We next used transwell to investigate whether EphA2 affects the ability of cancer cells to migrate and invade." (PMID 33712565, 2021). "Using an EphA2 internalization assay in cancer cell lines we recognized that, similar to the ephrin ligands, dimeric versions of these synthetic agents possessed greatly increased cellular efficacy in causing receptor degradation, compared to their monomeric versions." (PMID 34204178, 2021). "Notably, ECs can also regulate the transendothelial migration of cancer cells through the endothelial ligand EphrinA1, which binds to Ephrin-Type-A receptor 2 (EPHA2) on cancer cells." (PMID 34073394, 2021). "Interestingly, some lipoplexes formulations are currently investigated in clinical trials (ClinicalTrials.gov) for cancer treatment (Atu027, EphA2, DCR-MYC, TKM-08030)." (PMID 34863235, 2021). "Thus, unliganded EphA2 acts as a downstream effector of EGF receptors to promote cancer cell motility and invasion." (PMID 33572284, 2021). "EphA2 is the most frequently affected of all Eph receptors in human cancer." (PMID 33572758, 2021). "Eph receptor A2 (EphA2) is part of the receptor tyrosine kinase family that modulates cell differentiation, survival, and proliferation, and it is overexpressed in multiple cancer types." (PMID 34727233, 2021). "EphA2 signaling can affect the cell–cell interaction and motility of cancer cells." (PMID 33947097, 2021). "EphA2 is highly expressed in many cancers with important prognostic implications." (PMID 33572284, 2021). "Circulating EphA2 is an effective biomarker to diagnose malignant tumors." (PMID 33968283, 2021). "Therefore, subsequent research into EphA2’s role in KS development is required, which will potentially also shed light on the oncogenic role of EphA2 in other cancers." (PMID 33430066, 2021). "Indeed, EphA2 is upregulated in a number of cancers and, likewise, immunohistochemistry has demonstrated increased protein expression of EphA2 in KS skin tissue." (PMID 33430066, 2021). "However, EPHA2 cannot bind to its ligand efficiently in cancer tissues, resulting in abnormal EPHA2 signal transduction and cancer cell adhesion." (PMID 33834064, 2021). "EPHA2 expression has been reported as higher in cancer tissues compared with non-cancerous epithelium, elevated EPHA2 expression being associated with reduced OS, while EPHA2 and ephrin-A1 co-expression are correlated with recurrence rates." (PMID 34445116, 2021). "EphA2, as one of the well‐studied RTKs, has been a focus on cancer research for many years." (PMID 33586348, 2021). "The role of chemoattractants (e.g., EGF) and surface receptors (e.g., EphA2) as driving molecules controlling cell adhesion and migration in cancer has been a focus of study for many years, and has been exploited for targeting of drug delivery and cancer treatment." (PMID 35096972, 2021). "Speculatively, we propose that these phenomena could attenuate or amplify the effect of agonistic agents in different cancer cell lines, as we observed in the present report comparing the effect of agonistic agents in targeting EphA2 in MDA-MB-231 or BxPC3." (PMID 34204178, 2021).
cancer (continued). "Indeed, EPHA2 exhibited a striking alteration in its localization on the cancer organoids and cell lines, exhibiting diffuse expression rather than being restricted to cell-cell junctions, as previously reported for transformed cells." (PMID 33596248, 2021). "Our results support a role for EPHA2 in EBV entry into conventional cancer cell lines." (PMID 33596248, 2021). "ANXA1 also promotes the proliferation and metastasis of cancer cells through the binding of EphA2, the suppression of autophagy and the activation of the PI3K/AKT pathway and promotes proliferation and migration via the regulation of the IL-6/JAK2/STAT3 pathway." (PMID 34439260, 2021). "Low juxtacrine signaling and/or insufficient levels of ephrinA1 on cancer cells reduce EphA2 tyrosine phosphorylation and this leads to attenuated internalization and degradation of EphA2 receptor, with a relative increase of EphA2 levels." (PMID 33572284, 2021). "Therefore, ephrin-A1 and the receptor, EphA2 are also promising targets for cancer therapy, and ephrin-A1 shows potential as a serum biomarker of cancer." (PMID 33804570, 2021). "However, because of EphA2′s dual functions as both a tumor suppressor and oncogene in various cancers, further research is required to investigate if a similar mechanism is present in prostate cancer cells." (PMID 34884670, 2021). "Finally, potent cytolytic activity exerted by Vδ1 T cells was significantly reduced in EPHA2 knockouts in renal A-498 and colon HT-29 carcinoma cell lines." (PMID 34691070, 2021). "Only 1 of 20 patient samples showed EphA2 in <10% of cancer cells (5%)." (PMID 33092175, 2020). "However, an accumulating body of evidence suggests human EphA2 is abundantly expressed in diverse cancers such as prostate, lung, esophageal, colorectal, cervical, ovarian, and breast and skin cancers." (PMID 32811512, 2020). "Increases cancer stemness via modulation of the EphB2/EphA2 signaling in CRC CSc." (PMID 33489917, 2020). "Emerging evidence links high EphA2 protein amounts with EphA2 regulation at the mRNA level as well as protein stability, although the precise mechanisms governing EphA2 upregulation in cancer remain largely undefined." (PMID 32811512, 2020). "Overall, EphA2 represents a potential target for treating malignant tumors." (PMID 32811512, 2020). "Consequently, EphA2’s expression patterns and functional relevance in malignancies make this protein an attractive therapeutic target in cancer." (PMID 32811512, 2020). "For example, EphA2 could selectively deliver therapeutics to EphA2-overexpressing cancers while simultaneously regulating EphA2-signaling related events." (PMID 32811512, 2020). "Most of the genes in the 9-gene classifier (ITGB1, EPHA2, IL1R2) are involved in the migration, immune pathways, adhesion and metastasis of PDAC or other cancers, that are specifically associated with the developmental events and signaling in the progression of cancer." (PMID 33133160, 2020). "Moreover, it has been reported that EphA2 promotes cancer progression by pS897-EphA2-activating AKT/Stat3 signaling." (PMID 32848131, 2020). "As an EphA2 tyrosine kinase inhibitor, whether ALW-II-41-27 suppresses cancers by inhibiting pY772-EphA2 is unclear." (PMID 32848131, 2020). "EPHA2 is known to exhibit opposing roles towards cancer progression." (PMID 31484920, 2019). "Notably, such senescent sEVs were demonstrated to act as important players in promoting enhanced cancer cell proliferation via the Eph receptor A2 (EphA2)." (PMID 31137607, 2019). "In conclusion, the present results suggest that the EPHB6 mutation promotes cancer cell proliferation and migration/invasion and induces CAM-DR, and these effects are mediated by the stabilization of EPHA2 and the activation of downstream JNK/CDH11/RhoA/FAK signaling." (PMID 31160603, 2019).